RUSC1-AS1 (RUSC1 antisense RNA 1)
Synonyms: C1orf104; FLJ35976
Gene: Long non-coding RNA gene on chromosome 1 (155,316,856 to 155,324,385, reverse strand). Ensembl gene ENSG00000225855.
Diseases named in the same sentence as RUSC1-AS1 in open-access papers:
RUSC1-AS1 is named in the same sentence as 1 disease in open-access papers, as found by Europe PMC text mining. Sharing a sentence is not in itself a finding about the gene and the disease. The quoted sentences say what the papers report.
cancer (1 paper, 2021). A tumor composed of atypical neoplastic, often pleomorphic cells that invade other tissues. "Dysregulation of RUSC1-AS1 (also known as C1orf104) has been associated with several cancer types." (PMID 34440306, 2021).